IER3 (immediate early response 3)
Diseases named in the same sentence as IER3 in open-access papers (continued):
Sharing a sentence is not in itself a finding about the gene and the disease.
infection (16 papers, 2014 to 2025). The state of being infected such as from the introduction of a foreign agent such as serum, vaccine, antigenic substance or organism. "Subsequent analysis by m6A profiling revealed infection-specific differential methylation events, particularly in apoptosis-related genes such as IER3, thus providing insight into the role of m6A modification in the infection process." (PMID 40521032, 2025). "This suggests that IER3 not only plays a role in cellular stress responses but also contributes to regulating cell survival during infection." (PMID 40521032, 2025). "RIP-qPCR results showed that reduced YTHDF2 binding after infection resulted in decreased IER3 degradation and increased mRNA stability." (PMID 40521032, 2025). "One in vitro study of human macrophages, however, had high levels of IER3 mRNA following infection with a hypervirulent strain of M. tuberculosis indicating the transcriptional pathway is triggered." (PMID 38861581, 2024). "Ier3 transcription is triggered by cytokines, hormones, DNA damage, and infections." (PMID 38861581, 2024). "However, after infection, we observed 15 genes with significant differences between the two host genotype groups (Pt-test < 0.05), including IER3, VARS2 and ZNRD1 involved in immune response, ER stress and zinc homeostasis." (PMID 39613754, 2024). "To evaluate the functional impact of TRAIL/IER3 interactions within HCC cells, we next infected Huh7 and SMMC7721 cell lines with these adenoviral vectors as above and confirmed the efficiency of this infection approach." (PMID 33472635, 2021). "Supporting non-apoptotic cell death by aggregate infection, the genes we observed to be upregulated in this study with aggregate infection include IER3, which has been shown to be involved in the negative regulation of apoptotic cell death." (PMID 34925266, 2021). "Though IFI27 was induced following infection of A549-ACE2 cells, it was not induced in infected SVC, nor was IER3 induced in any sample." (PMID 36137009, 2022).
kidney disease (2 papers, 2010 to 2012). "We found that lcn2, cfi, pla2g7, and ier3 were upregulated by kidney disease progression." (PMID 22970174, 2012). "Neither MCL1 nor IER3 have been studied in the context of primary GN, and further studies will be necessary to better define their role in kidney disease." (PMID 20976140, 2010).
metabolic disease (2 papers, 2016 to 2025). A congenital disorder (due to inherited enzyme abnormality) or acquired (due to failure of a metabolically important organ) disorder resulting from an abnormal metabolic process. "Gene annotation based on the TWAS database highlighted significant associations between several of these candidate genes (such as SPP1, FAM13A, NDRG1, and IER3) and key bovine health traits, including milk protein percentage, body depth, and ketosis (a metabolic disease of dairy cow) susceptibility." (PMID 40521032, 2025).
IER3 also shares sentences with these, for which no sentence is quoted: cardiac hypertrophy (3 papers); acute kidney injury (2); acute myeloid leukemia (2); Arthritis (2); bacterial infection (2); Crohn disease (2); Hodgkins lymphoma (2); Insulin resistance (2); liver cancer (2); oral squamous cell carcinoma (2); osteoarthritis (2); rheumatoid arthritis (2); ulcerative colitis (2); age-related macular degeneration (1); amyotrophic lateral sclerosis (1); Arrhythmia (1); brain cancer (1); brucellosis (1); cardiovascular diseases (1); childhood cancer (1); chronic kidney disease (1); colon cancer (1); Coma (1); cystadenoma (1); diabetic retinopathy (1); dilated cardiomyopathy (1); esophageal squamous cell carcinoma (1); gastric cancer (1); haematological disorders (1); HCMV infection (1).
A further 19 diseases each share a sentence with IER3 in 1 paper.